CTLA4 (cytotoxic T-lymphocyte associated protein 4)
Diseases named in the same sentence as CTLA4 in open-access papers (continued):
Sharing a sentence is not in itself a finding about the gene and the disease.
tumor (continued). "MiR-138 targets CTLA-4 and PD-1, promoting tumor-regression by inhibiting tumor-infiltrating Tregs." (PMID 30319616, 2018). "In the microenvironment of GBM, hypoxia triggers the activation of immunosuppressive pathway, polarization of tumor associated macrophages, and overexpression of immune checkpoint genes, PD-L1 (programmed death-ligand 1) and CTLA-4 (cytotoxic T-lymphocyte-associated protein 4)." (PMID 29507709, 2018). "Only one of these tumors (that was either autophagy-competent or-deficient) was irradiated in the context of CTLA4 inhibition, and the response of both the irradiated and non-irradiated (abscopal) tumor was monitored." (PMID 30400822, 2018). "CTLA-4 signaling has been shown to dampen immune responses against infections and tumor cells." (PMID 29644214, 2018). "LY3300054 is shown to induce primary T cell activation in vitro, increase T cell activation in combination with anti-CTLA4 antibody, and to potently enhance anti-tumor alloreactivity in several xenograft mouse tumor models with reconstituted human immune cells." (PMID 29712568, 2018). "The use of CTLA-4 blockade to release this brake results in increased infiltration of T cells into tumors and may limit Treg cell infiltration in tumor microenvironment (TME), preventing suppression of cytotoxic T cell activity by these Treg cells." (PMID 29482595, 2018). "Inhibition of CTLA-4 signaling can also reduce T-regulatory cell function, which may contribute to a general increase in T cell responsiveness, including the anti-tumor immune response." (PMID 28219375, 2017). "Similarly, a key anti-tumor property of anti-CTLA-4 antibodies has been attributed to their ability to reduce Tregs as well." (PMID 28920002, 2017). "Moreover, the tetrameric form of the anti-CTLA4 aptamers significantly reduced the dosage to elicit anti-tumor responses in vivo." (PMID 28325295, 2017). "Thus, IFNβ responsiveness is required in both, the tumour and the host, for optimal induction of anti-tumour immunity by radiation and anti-CTLA4." (PMID 28598415, 2017). "Similarly, rejection of the irradiated and abscopal MCA38 tumours in mice treated with 8GyX3+anti-CTLA4 was abrogated in IFNAR1−/− mice." (PMID 28598415, 2017). "James Allison characterized the anti-tumor effect of antibody targeting CTLA-4." (PMID 28122590, 2017). "Six of the mAb disrupt inhibitory immune checkpoint signals by binding to the programmed cell death protein 1 (PD-1) receptor on the T cells (nivolumab and pembrolizumab), to PD-L1 on the tumor cells (atezolizumab, durvalumab, and avelumab) or to CTLA-4 on T cells (ipilimumab)." (PMID 29312320, 2017). "Because of its ability to inhibit tumor immunosuppressive mechanisms and increase tumor antigen presentation from direct tumor cell killing, imatinib is a promising candidate to synergistically enhance the antitumor T-cell activation generated by CTLA-4 blockade immunotherapy." (PMID 28428884, 2017). "We postulate that the therapeutic benefit observed in our study is a consequence of vorinostat-induced increase in tumor cells immunogenicity through HLA-DR up-regulation, associated with increase in T cells recognition, function and activation by anti-PD1 and anti-CTLA-4 blockades." (PMID 29371976, 2017). "Therefore, anti-CTLA4 can replace anti-PD-L1 in the triple regimen to cure mice bearing large Hepa1-6 tumors with the induction of tumor-specific immune responses." (PMID 28881713, 2017). "Due to their intimate interaction with tumor cells, the assessment of CTLA-4+ immune cells infiltrating the tumor epithelial compartment may have added significant value to the study." (PMID 28707078, 2017). "As our PsV therapeutic strategy targets innate immunity as well as adaptive immunity against tumours, combination of PsV with CTLA-4/PD-1/PD-L1/2 blockade approaches is expected to yield promising success in patients who failed in these checkpoint blockade therapies." (PMID 28397782, 2017).
tumor (continued). "However, the mechanisms by which CTLA-4 inhibition boosts tumor-specific T cell activity are unclear but the efficacy of CTLA-4 blockade is correlated with the emergence of new T-cells primed against neo-antigens." (PMID 29285320, 2017). "This remarkable success provides the rationale for ongoing clinical investigation of combined PD-1/PD-L1 and CTLA-4 inhibition in many different tumor types and the exploration of PD-1/PD-L1 inhibition in combination with inhibition of other immune checkpoints such as Tim-3 and Lag-3." (PMID 28239469, 2017). "In the B16 model, RFA and cryoablation have also been combined with a checkpoint blockade antibody directed against CTLA-4, resulting in increased numbers of tumor-specific T cells with increased IFN-γ secretion potential, and protection against outgrowth of tumor rechallenges." (PMID 27585790, 2017). "Impaired immune recognition may thus occur when a high fraction of CTLA-4 or PD-1 positive T-cells are found in the tumour microenvironment, or when the tumour itself expresses increased PD-L1 or PD-L2." (PMID 28571578, 2017). "Accumulating evidence suggests that anti-CTLA-4 works primarily in the secondary lymphoid organs by releasing pre-existing T cells from inhibitory signaling to target tumor neoantigens and by depleting Tregs in the tumor microenvironment." (PMID 28515726, 2017). "Thus, the complex structure presented here would be helpful for the design of small molecular inhibitors for CTLA-4 to improve anti-tumor efficacy." (PMID 28978021, 2017). "Given that gMDSC express very high levels of PD-L1, we assessed whether enhanced tumor rejection following gMDSC depletion plus CTLA-4 mAb was primarily through elimination of PD-L1 from the TME." (PMID 28915554, 2017). "Interestingly, co-administration of anti-CTLA-4 and PD-1 antibodies reverses T cell exhaustion by increasing effector T cell activity and cytokine production and hence augmenting tumor inhibition." (PMID 28220121, 2017). "This may be explained by the fact that the mismatch repair-deficient tumors create a microenvironment full of immune checkpoint ligands including PD-1, PD-L1 and CTLA-4 to evade tumor elimination." (PMID 28915720, 2017). "Similarly, it has been shown that compared with combination with anti-TGF or anti-IL-10R, combination with anti-CTLA-4 strikingly improves the therapeutic effect of VSV-mediated tumor regression by eliciting CD4+ and CD8+ T cells response." (PMID 28567163, 2017). "Using array-based analyses, significant differences in the CpG-methylation patterns between tumor tissues and matched controls were observed for CTLA4 and PDCD1 (PD1) (FDR < 0.01): NSCLC tumors exhibited a decreased degree of CpG-methylation in these loci compared to tumor-free tissues." (PMID 28503213, 2017). "The addition of ISF35 overcomes the primary resistance to the checkpoint blockade antibodies, anti-PD-1 and anti-CTLA-4, and generates potent systemic antitumor T cell immunity that eradicates the injected tumor as well as distant, uninjected tumors, including the brain." (PMID 29129918, 2017). "This hypothesis was supported by recent studies indicating that CTLA-4 or PD-1 blockade combined with the inhibition of the extracellular adenosine or A2AR/A2BR signaling resulted in a stronger anti-tumor effect." (PMID 28592285, 2017). "We and others have previously shown that simple baseline counts of peripheral blood cells may reflect a general immune status more prone or refractory to mount anti-tumor responses upon CTLA-4 inhibition." (PMID 29108362, 2017). "Studies to determine whether selumetinib would impact the anti-tumor activity of anti-CTLA-4 treatment were conducted in the CT26 model." (PMID 28807001, 2017). "The blockade of CTLA-4 can promote anti-tumor T cell immunity." (PMID 28416753, 2017).
tumor (continued). "Combination therapy of tumor-bearing mice with the vaccine archaeosome-OVA, and α-CTLA-4 administered concurrently as well as α-PD-1 and an α-PD-L1 antibody administered starting 9 days after tumor challenge given on a Q3Dx4 schedule (days 9, 12, 15 and 18), significantly enhanced survival." (PMID 29072624, 2017). "Notably, depletion of CD8+ T cells abrogated abscopal responses and complete tumour regression in mice treated with anti-CTLA4 and 8GyX3." (PMID 28598415, 2017). "Moreover, Trex1 knockdown in TSA cells in the irradiated tumour restored the ability of radiation used at 20 Gy with anti-CTLA4 to induce abscopal responses." (PMID 28598415, 2017). "Within the tumours of treated animals, CTLA-4 blockade gave rise to a significantly altered expression of markers associated with dysfunction (PD-1, Lag-3 and CD160), activation (CD25, GITR and CD38), as well as co-stimulation and development (CD27 and CD127) on mLama4-specific T cells." (PMID 28916749, 2017). "Having found that the IS score reflected response to anti-CTLA-4 immunotherapies, we applied the IS to gene expression data from TCGA pan-cancer data including samples of 30 tumor types (N = 9081) to estimate the potential response rate of each cancer lineages to immunotherapy." (PMID 29051489, 2017). "Thus, tumor patients with CTLA-4 +49AA genotype would be expected to have an enhanced suppression on T cell activity and immune function, which contribute to the poor prognosis of cancers." (PMID 28211499, 2017). "Consequently, inhibitors of CTLA4 and PD-1 have been shown to exert effective anti-tumor activity against a variety of malignancies in preclinical and clinical studies." (PMID 28536354, 2017). "We next combined gMDSC depletion with CTLA-4 mAb checkpoint inhibition in MOC1 tumor-bearing mice." (PMID 28915554, 2017). "It has been hypothesized that anti-CTLA-4 for tumor immunotherapy is achieved by releasing brakes on both regulatory T cells (Tregs) and conventional T cells." (PMID 28978021, 2017). "First, Elenagen, similar to antibodies and other vaccines, and anti-CTLA4, in contrast to conventional therapeutics, does not evoke objective response (i.e. complete + partial response), but produces tumor control better than most other vaccines, antibodies, or anti-CTLA4." (PMID 28881846, 2017). "Whether the differences of anti-tumor efficacy is dependent on the intervention of CTLA-4/B7-1 (or B7-2) interaction or Fc-mediated ADCC/CDC activity remains unknown." (PMID 28978021, 2017). "We subsequently provide evidence that upregulation of interferon response genes mediates this effect, and show that the clinically relevant HSP90 inhibitor ganetespib potentiates responses to anti-CTLA4 and anti-PD-1 immunotherapy in a preclinical murine tumor model." (PMID 28878208, 2017). "In addition, experimental model systems have revealed that antibodies targeting CTLA-4 deplete Treg in the tumor microenvironment." (PMID 27714433, 2017). "Furthermore, therapeutic targeting of CTLA-4 or PD-1 was also proved to achieve durable tumor regression in NSCLC, bladder cancer, and renal cell carcinoma." (PMID 28536525, 2017). "CTLA-4 blockade combined with IDO inhibitors strongly synergizes to mediate tumor rejection." (PMID 28970830, 2017). "Therefore, we nourished the blockade of CTLA-4 with trAbs that specifically redirect T cells to TAAs and activate the T cells in the presence of tumor cells." (PMID 27966460, 2017). "The expression of CTLA-4 was enriched in both CD8 and non-CD8 T cells in the tumour relative to the blood with varying proportions of CTLA-4+ T cells which might predict a widely varied response to checkpoint blockade therapies." (PMID 28423034, 2017).
tumor (continued). "For instance, programmed cell death-1 (PD-1)/PD-L1 axis, and the cytotoxic T-lymphocyte antigen 4 (CTLA-4)/B7 axis, which contribute cancer cell protection through their suppressive role in tumor microenvironment and negatively regulate cancer cell eradication by immune destruction methods." (PMID 28785557, 2017). "STING might also play a role in influencing the anti-tumor effects of checkpoint inhibitors such as CTLA4 and PD135." (PMID 28176788, 2017). "Therefore, we determined CD69 and CTLA-4 levels at different time points after in vitro incubation of T cells isolated from mouse spleens together with DCs and tumor cells (B78-D14 or B16-EpCAM) in the presence of Surek or BiLu." (PMID 27966460, 2017). "However, T-cell activation is limited by both the recruitment of T-regs (expressing CTLA-4) into the tumor stroma and the suppression of any activated T-cells by GBM expression of PD-L1." (PMID 28730140, 2017). "In addition, broader and more frequent T cell responses against common tumour antigens were detected in patients treated with Ipilimumab as compared to anti-CTLA-4 naïve patients." (PMID 28423678, 2017). "CTLA-4 was not elevated in MPNST cell lines or tumor-associated Schwann cells compared with normal human Schwann cells." (PMID 29137242, 2017). "Further, our finding that CTLA-4 mAb treatment reduced tumor infiltrating Tregs by roughly 50% suggests that Treg depletion may account for some of the immune stimulatory effects observed with CTLA-4 mAb treatment." (PMID 28915554, 2017). "Inhibition of CTLA-4 leads to significantly increased immune recognition of tumor cells." (PMID 29179523, 2017). "Having confirmed that 20 Gy and 30 Gy single dose were similarly ineffective, and that abscopal effects with anti-CTLA4 could be observed only after repeated 8 Gy doses, we then studied the differences in tumour response to 20 Gy and 8GyX3." (PMID 28598415, 2017). "Given that perineural tumours are infiltrated by immune T cells that fail to clear the tumour, we have analysed whether inhibitory receptors such as PD-1, CTLA-4 and Tim-3 are expressed on the surface of tumour-derived T cells using blood as a comparator." (PMID 28423034, 2017). "Based on this understanding, anti-CTLA-4 (inhibition of the negative regulator) has been shown to induce tumor antigen-specific T cell immunity (adoptive immunity) and many clinical trials have been developed using this anti-CTLA-4 based T cell immunity induction." (PMID 29179527, 2017). "Tumor cells can exhaust T cells by expressing coinhibitory molecules, such as CTLA-4 and PD-L1." (PMID 28977947, 2017). "In context of cancer, it is suggested that CTLA-4 expression on low-affinity tumor specific T cells attenuates their proliferation which could be possibly overcome by CTLA-4 blockade." (PMID 28073373, 2017). "Therefore, we subcutaneously injected 5 × 105 B16ova cells into wild-type or Cblb−/− mice, treated them with anti-CTLA-4, anti-PD-L1 or IgG control antibodies and monitored tumor growth." (PMID 28611299, 2017). "In addition, the number of tumor-infiltrating MDSCs and Tregs and immunosuppressive markers of CTLA-4 and PD-1 on T cells were suppressed in shReg3g mice, but the frequency of CD8+ T cells and the expression of TCR in T cells were increased." (PMID 28880262, 2017). "Hence, high stromal CTLA-4 expression presumably reflects a tumor microenvironment highly infiltrated by activated immune cells, even though immunosuppressive subtypes such as regulatory T cells and exhausted cytotoxic T cells also express CTLA-4." (PMID 28707078, 2017). "Immunohistochemistry studies suggest that perineural tumour contains a lymphocyte infiltrate but it is difficult to quantitate the different proportions of immune cell subsets and expression of checkpoint molecules such as PD-1, Tim-3 and CTLA-4." (PMID 28423034, 2017).
tumor (continued). "Importantly, while CTLA-4 seems to regulate early T-cell activation, PD-1 inhibits effector T-cell activity in the effector phase within tissue and tumours." (PMID 28404796, 2017). "However, selumetinib treatment reduced baseline tumor expression of Arg1, and reverses the increased Arg1 expression induced in tumor cells by CTLA-4 blockade." (PMID 28807001, 2017). "It was shown in mouse models that this peptide overcomes tumor resistance to CTLA-4 ICKB." (PMID 28970830, 2017). "CTLA-4 traffic and the expression of this molecule are modified by the tumor environment." (PMID 28470464, 2017). "Treatment with CTLA-4 mAb alone induced tumor rejection in 5 of 11 mice treated." (PMID 28915554, 2017). "In this study, we characterised the immune response of resected BTCs and observed that the deregulation of immunomodulatory transcripts in peritumoural areas can create an immunosuppressive milieu that facilitates tumour relapse, likely through the activation of the CTLA4 axis." (PMID 28988016, 2017). "However, the percentage of CTLA-4+ T cells increased significantly in HNSCC tumor microenvironment (10.0 ± 7.5%; p < 0.0001)." (PMID 28574843, 2017). "The most pronounced differences, however, were seen in the expansion and activation of the intratumoral CD8+ lymphocytes, an effect that was further augmented by combination with systemic CTLA-4 blockade and was seen in the virus-injected tumours, distant tumours and spleen." (PMID 28194010, 2017). "Interestingly, anti-CTLA4 treatment also led to a significant improvement in control of the irradiated tumour in mice treated with 8GyX1." (PMID 28598415, 2017). "IDO inhibitors, such as 1-methyl-D-trytophan (indoximod) and epacadostat, enhance anti-tumor immunity either alone or in combination with mAbs against CTLA-4 or PD-1 in murine models or in studies with CD19-CAR T cells in humanized mouse models and are presently in clinical trials." (PMID 28239463, 2017). "Notably, E7046 also showed synergistic anti-tumor activity when combined with anti-CTLA-4 antibodies, which have been reported to diminish intratumoral Tregs." (PMID 28920002, 2017). "Importantly, while direct trAb-mediated destruction of tumor cells was only moderately improved by combination with CTLA-4 inhibition, the immunologic memory elicited by the combination treatment was indeed considerably enhanced." (PMID 27966460, 2017). "Furthermore, CTLA-4 and PD-1 expression in peripheral blood and tumor-infiltrating lymphocytes increases with immune checkpoint inhibition, reflecting the expansion of effector T-cell populations that would otherwise have been apoptotic or dysfunctional." (PMID 29207684, 2017). "However, elevated levels of cytotoxic T-lymphocyte-associated protein 4 (CTLA-4), programmed death 1 (PD-1)/programmed death ligand 1 (PD-L1), B7-H3, and B7-H4 on CD8+ tumor-infiltrating lymphocytes (TILs) have been shown in NSCLC." (PMID 28434399, 2017). "Blocking of CTLA-4 in Cblb−/− mice prolonged survival and attenuated tumor growth to an even more pronounced extent than in IgG-treated Cblb-deficient mice, suggesting that CTLA-4 signaling is not completely dependent on Cbl-b." (PMID 28611299, 2017). "Finally, we show that pre-treatment, but not concurrent treatment, with selumetinib enhanced the anti-tumor activity of anti-CTLA-4 in the CT26 model." (PMID 28807001, 2017). "Therefore, the combined inhibition of the PD-1/PD-L1, and CTLA-4/B7 axis has been established to be an effective anti-tumor treatment strategy for patients with various malignancies." (PMID 28878676, 2017). "In the bilateral flank tumour models, intratumoral administration of NDV-ICOSL results in enhanced infiltration with activated T cells in both virus-injected and distant tumours, and leads to effective rejection of both tumours when used in combination with systemic CTLA-4 blockade." (PMID 28194010, 2017). "Tumor tissue expression biomarkers were addressed in 11 CTLA-4 ICI studies and 16 PD1 ICI studies." (PMID 29034210, 2017).